NOX4 (NADPH oxidase 4)
Diseases named in the same sentence as NOX4 in open-access papers (continued):
Sharing a sentence is not in itself a finding about the gene and the disease.
liver fibrosis (continued). "Thus, NOX4 plays an essential role in the development of hepatic fibrosis." (PMID 31130857, 2019). "During liver fibrosis, NOX4 is required for both HSC activation and maintenance of the activated phenotype in MFB in a TGF-β-dependent manner and mediates the TGF-β pro-apoptotic response in hepatocytes, which might be relevant to blunt regeneration and create a pro-fibrogenic microenvironment." (PMID 30250825, 2018). "Furthermore, hepatic stellate cells (HSCs), which have a key role during liver fibrosis, induce NOX4-dependent ROS formation upon stimulation with TGF-β1 and the down-regulation of NOX4 by siRNA or the absence of NOX4 in mice inhibits the TGF-β-induced fibrotic process." (PMID 27345301, 2016). "Therefore, we aimed to determine the role of NOX1 and NOX4 in liver fibrosis, and investigated whether NOX1 and NOX4 signaling mediates liver fibrosis by regulating HSC activation." (PMID 26222337, 2015). "Finally, the finding that NOX4 is induced during the progression of a HCV disease reinforces the hypothesis of a role for NOX4 in human liver fibrosis." (PMID 23049784, 2012). "However, very few were known about the role of NOX4 in liver fibrosis." (PMID 23049784, 2012). "Results presented in this manuscript support that NOX4 could play an essential role inducing activation of stellate cells and apoptosis of hepatocytes under these conditions of human disease, contributing to the development of liver fibrosis." (PMID 23049784, 2012). "Another study suggested that NOX4 expression was increased in TGF-β-treated HSCs and CCl4-induced mice liver fibrosis." (PMID 35035671, 2022). "NOX-es are also involved in activating HSCs, responsible for liver fibrosis, and this mechanism itself can trigger upregulation of diverse NOX isoforms (NOX1, NOX2 and NOX4), creating a vicious cycle and potentially sustaining the progression toward HCC." (PMID 35740032, 2022). "Experimental liver fibrosis induced by carbon tetrachloride was attenuated in both NOX1 and NOX4-knock-out mice and this effect was reproducible by treatment with a dual NOX1/NOX4 inhibitor." (PMID 35740032, 2022). "The IHC results showed that the expression of NOX4 and NLRP3 was upregulated in mice with CCI4 induced liver fibrosis, and after UA treatment, the expression of NOX4 and NLRP3 was significantly reduced (P < .050)." (PMID 34530693, 2021). "Our study showed that UA improved the intestinal bacteria by inhibiting the NOX4/NLRP3 inflammasome signaling pathway, thereby restoring liver function and slowing the occurrence and development of liver fibrosis." (PMID 34530693, 2021). "Not only NOX4, but also NOX1 plays important roles in the progression of hepatic fibrosis, promoting proliferation and activation of HSCs." (PMID 34571961, 2021). "We previously found that activation of NOX4 in HSECs of either CCl4‐ or BDL‐induced liver fibrosis rat models generated abundant ROS to promote HSECs defenestration and liver fibrosis." (PMID 33522656, 2021). "Alternatively, we have discovered that BRG1 fuels ROS production in endothelial cells by activating the transcription of NADPH oxidase 4 (NOX4); ROS accumulation in turn drives EndMT to promote liver fibrosis in mice." (PMID 32478075, 2020). "Profibrotic factors NOX4 and RhoA participate in the activation of HSC and accelerate the development of liver fibrosis." (PMID 32083022, 2020). "We have previously shown that endothelial-specific deletion of BRG1 in mice attenuates bile duct ligation (BDL) and thioacetamide induced liver fibrosis by regulating the transcription of caveolin-1 (CAV1) and NADPH oxidase 4 (NOX4), respectively." (PMID 32478075, 2020). "We have demonstrated that Rac1 is involved in NOX activation and that NOX4/ROS can also induce HSC activation by activating the RhoA/ROCK1 signaling pathway, thereby promoting liver fibrosis." (PMID 32083022, 2020).
liver fibrosis (continued). "Inhibition of NOX1/NOX4 using GKT137831 attenuated CCl4 or BDL-induced ROS production and hepatic fibrosis in mice." (PMID 26869935, 2016). "For example, inhibition of NOX4 via genetic deletion, antisense oligonucleotides, siRNA, or NOX inhibitors attenuated disease progression in rodent models of pulmonary, renal, and liver fibrosis." (PMID 24701562, 2014). "In particular, NOX4 plays a significant role in ROS production, and is highly expressed in hepatocytes, liver sinusoidal endothelial cells, hepatic stellate cells (HSC), and myofibroblasts during the progression of liver fibrosis." (PMID 40060764, 2025). "β-arrestin-2 may also enhance NADPH oxidase 4 (NOX4) expression and reactive oxygen species (ROS) which are significant factors in liver fibrosis via ERK and JNK signaling." (PMID 37843713, 2023). "For example, during liver fibrosis, Aoyama and colleagues revealed that the excessive activation of NOX1 in hepatic stellate cells upregulated NOX4 expression, which greatly induced ROS generation and suggested that NOX1/4 were promising therapeutic targets for liver fibrosis." (PMID 35386842, 2022). "Recently, a study showed that ursolic acid, a natural terpenoid isolated from a variety of herbal medicine, decreased collagen deposition and fibrosis-related factors expression and inhibited the level of NADPH oxidase 4 (NOX4) and NLRP3 in the CCl4-induced liver fibrosis model." (PMID 36160411, 2022). "The role of macrophage NOX4 in liver fibrosis has not been directly assessed by currently available studies." (PMID 35740032, 2022). "Further review of the literature showed that both TGFβ1 and AngII could upregulate the expression of NOX4, and GKT137831, a dual inhibitor of NOX1/4, could inhibit the production of ROS and hepatic fibrosis." (PMID 34135982, 2021). "Moreover, IL11 and NOX4 in particular are critically involved in mediating downstream TGF-β effects in cardiovascular and liver fibrosis as well as systemic sclerosis." (PMID 33440877, 2021). "Co-expression between lncRNA-Met and lncRNAs-Nox4 may activate HSCs through oxidation-reduction processes and PI3K/Akt signaling pathway, increase the production of ECM, and regulate the process of liver fibrosis." (PMID 34597331, 2021). "We aimed to determine the relationship between NOX4/ROS and RhoA/ROCK1 in liver fibrosis." (PMID 32496208, 2020). "Compared to that in the CCl4 group, the mRNA level of NOX4 in the RhoAi group was decreased to a certain degree, but this difference was not statistically significant, indicating that NOX4/ROS is the upstream signalling pathway of RhoA/ROCK1 in liver fibrosis." (PMID 32496208, 2020). "In conclusion, our results indicate that NOX4/ROS and RhoA/ROCK1, which may interact, play an important role in the development of liver fibrosis." (PMID 32496208, 2020). "NOX4 mediates the signal transduction of major pro-hepatic fibrosis factors, such as TGF-β, leading to HSC activation and hepatocyte apoptosis and thus plays an important role in liver fibrosis." (PMID 32496208, 2020). "NOX4 was not only upregulated in myofibroblastic foci in IPF, but also in nonalcoholic steatohepatitis and in hepatitis C virus-induced fibrosis, and deleting the Nox4 gene proved beneficial in several animal models of lung and liver fibrosis." (PMID 33059312, 2020). "NOX4, an important subtype of the NOX family, has been shown to induce the conversion of HSCs to myofibroblasts (MFBs) by releasing ROS, which is closely related to liver fibrosis." (PMID 32496208, 2020). "We investigated the interaction between NOX4/ROS and RhoA/ROCK1 during liver fibrosis and whether these molecules are targets for the anti-fibrotic effects of UA." (PMID 32496208, 2020). "There is evidence to suggest that NOX4 is involved in EMT and liver fibrosis." (PMID 31750301, 2019).
liver fibrosis (continued). "These experiments indicate that interventions to reduce NOX4 or to increase CCR2/CCL2 turnover may attenuate ethanol mediated oxidative stress in HSC at early stages, that later on may result in decreased liver fibrosis." (PMID 28383062, 2017). "Activated HSCs and ROS generation are also attenuated in HSCs lacking NOX1 and NOX4, suggesting NOX1 and NOX4 play important roles in liver fibrosis and injury through regulating inflammation, proliferation and fibrogenesis in HSCs." (PMID 26222337, 2015). "Nonetheless, several studies have successfully employed a dual NOX1/NOX4 inhibitor GKT137831, which showed promising results in mouse models of liver fibrosis and hypoxia-induced pulmonary hypertension and is currently entering a phase II clinical trial for diabetic nephropathy." (PMID 24701562, 2014). "NOX4 is widely distributed in liver tissue, producing O2•− and H2O2 as its primary products, suggesting that therapeutic targets and antioxidant agents to suppress NOXs may constitute an alternative treatment for liver fibrosis." (PMID 38001866, 2023). "Specific liver-knockout of PTP1B protected mice from chronic alcohol plus binge-induced oxidative stress, liver fibrosis and inflammation via the inhibition of nuclear factor kappa B (NF-κB) and reduction of nicotinamide adenine dinucleotide phosphate oxidase 2 (NOX2) and NOX4 expression." (PMID 34566665, 2021). "Thus, while the presence of NOX4 is beneficial in acute colitis, elevated H2O2 levels due to NOX4 upregulation may drive intestinal fibrosis, similar to observations in lung and liver fibrosis." (PMID 33059312, 2020). "Recent evidences show up the dual role of NOX1/NOX4 pharmacological inhibitors in decreasing both the apparition of fibrogenic markers and hepatocyte apoptosis in vivo, highlighting the relevance of NOX1 and NOX4 in liver fibrosis and opening new perspectives for its treatment." (PMID 30250825, 2018). "Consistent with our findings, NOX4 has been shown to play a role in TGF-β-dependent fibroblast-to-myofibroblast transdifferentiation in several normal tissues, and its inhibition has been shown to attenuate pulmonary and liver fibrosis in preclinical mouse models." (PMID 28922779, 2018). "In addition to the TGFβ-NOX4 axis-mediated activation of HSC and expression of fibrogenic factors, other NOX isoforms, including NOX1, NOX2, and NOX2 regulatory subunit p47phox, are also reported to orchestrate the progression of hepatic fibrosis." (PMID 26869935, 2016). "Targeting specific NOX isoforms with specific inhibitors, such as NOX1 and/or NOX4 to prevent HSC activation and protect hepatocyte injury may be promising to treat liver fibrosis, although future work is needed to fully confirm the clinical safety of these compounds." (PMID 26869935, 2016). "However, whether FA can treat liver fibrosis has not been studied so far, and whether it plays an anti-hepatic fibrosis role through NOX4/ROS pathway needs to be researched." (PMID 35035671, 2022). "Although MF was able to attenuate HSC activation and liver fibrosis by inhibiting TGF-β1/SMADs and NOX4/ROS signaling pathways, there was no alteration of PTP1B activity observed after MF administration." (PMID 34566665, 2021). "The mechanism of interaction between NOX4/ROS and RhoA/ROCK in liver fibrosis has not been determined, although both NOX4/ROS and RhoA/ROCK are involved in regulating HSC activation in association with the progression of fibrotic disease." (PMID 32496208, 2020). "Interestingly, in vivo experiments on NOX4-/- mice showed that the liver fibrosis induced by CCl4 was significantly improved compared with that in WT CCl4 mice, and neither Fasudil nor UA could further improve the liver fibrosis of NOX4-/- mice." (PMID 31130857, 2019).
liver fibrosis (continued). "Activated HSC and ROS generation are also attenuated in HSC lacking NOX1 and NOX4, suggesting NOX1 and NOX4 play important roles in liver fibrosis and injury through regulating inflammation, proliferation and fibrogenesis in HSC." (PMID 30250825, 2018). "The interaction between NOX4/ROS and RhoA/ROCK1 in liver fibrosis is not yet clear." (PMID 32496208, 2020).
heart failure (59 papers, 2010 to 2026). Inability of the heart to pump blood at an adequate rate to meet tissue metabolic requirements. "In summary, experimental studies in mice indicate that NOX4 induction aggravates cardiac dysfunction and pathological remodeling in heart failure, while loss-of-function approaches consistently mitigate these deleterious effects." (PMID 41009041, 2025). "High-dose EPO also increased heart failure-associated genes such as Cdk8, Nox4, S100A, and SERCA2a, and hypertrophic cardiomyopathy-related genes such as Acta1, Myh7, Nppa, and Nppb in male WT mice but not in ΔEPORE male mice." (PMID 38628440, 2024). "In nNOS−/− mice, the expression levels of heart failure-associated genes Cdk8, TGFβ2, and NOX4 and hypertrophic cardiomyopathy-related gene Nppa were analogous to levels in WT mice." (PMID 38628440, 2024). "ΔEPORE mice showed increased expression of two-fold or more of heart failure-associated genes Cdk8, TGFb2, Nox4, S100A, and SERCA2a." (PMID 38628440, 2024). "A recent study demonstrated that skeletal muscle specific knockout for Nox4 provided full protection against the loss of diaphragm maximal force, while the knockout of Nox2 provided partial protection in mice with heart failure." (PMID 37362442, 2023). "In summary, these studies implicate NOX2 and to a lesser extent NOX4 in metabolic causes of heart failure including obesity, high-fat diet, and diabetes." (PMID 35325070, 2023). "Overproduction of ROS derived from NOX4 was recently demonstrated to cause myocardial apoptosis and necroptosis, leading to heart failure via activation of RIP3 in cardiac myocytes." (PMID 35148678, 2022). "NOX1 and NOX2 activity enhanced in the coronary arteries from patients with coronary artery disease, whereas there seems a critical role of oxidative stress caused by NOX2 and NOX4 in the progression of heart failure." (PMID 34440716, 2021). "It evades the risk of chronic therapy and the rather double-edged role of NOX4 in heart failure and angiogenesis." (PMID 22648375, 2012). "The functional diversity of NOX4 splice variants, from their influence on ROS generation to their potential involvement in DNA damage signaling and heart failure, emphasizes the importance of understanding the specific roles of each isoform in different cellular contexts and disease states." (PMID 41009041, 2025). "In human heart failure, most studies report increased NOX4 expression in the failing myocardium, though causality remains unclear." (PMID 41009041, 2025). "It has been reported that ROS derived from NOX4 in the mitochondrial membrane might cause mitochondrial dysfunction and cardiac myocyte apoptosis during aging and heart failure." (PMID 35648750, 2022). "Thus, the studies suggest the role of oxidative stress caused by NOX2 and NOX4 in the progression of heart failure." (PMID 34440716, 2021). "Additionally, NADPH oxidase-4 (Nox-4) enhances fatty acid utilization and alleviates cardiac dysfunction in pressure overload-induced heart failure by increasing the O-linked N-acetylglucosamine (O-GlcNAcylation) of CD36." (PMID 34094645, 2021). "Disease specific expression pattern of NOX4 isoforms may provide new diagnostic and therapeutic targets in heart failure, and disease-specific splicing events might represent a new factor to consider when developing NOX4-modulator drugs." (PMID 29204124, 2017). "It is also noteworthy that NOX2 and NOX4 contribute to atrial oxidative stress and susceptibility to atrial fibrillation, a comorbidity that is present in roughly one third of patients with HFpEF that can result in chronic arrhythmogenicity that precipitates the progression of cardiac failure." (PMID 36139898, 2022). "Taken together, direct targeting of NOX4 has shown promises in attenuating oxidative stress, inflammation, fibrosis and dysfunction across preclinical models of heart failure, myocardial infarction, I/R injury, AF and diabetic cardiomyopathy." (PMID 41009041, 2025).
heart failure (continued). "Their study revealed extensive alternative splicing of NOX4 in heart failure samples, compared to healthy donor hearts." (PMID 41009041, 2025). "Together, these findings indicate that NOX4 silencing can blunt pathological hypertrophy and fibrosis in models of heart failure." (PMID 41009041, 2025). "Contradictory evidence, including reports of unchanged or even reduced NOX4 levels in specific heart failure subtypes, further underscores the complexity of its role." (PMID 41009041, 2025). "Animal studies demonstrate that antioxidant therapies or inhibitory NOX4 targeting can mitigate some of the pathological effects of heart failure." (PMID 41009041, 2025). "In heart failure, it is predominantly Nox4 that mediates ROS production, and Nox4 is located in cardiomyocytes." (PMID 38628644, 2024). "NADPH oxidase 4 (NOX4) is an enzyme that is the primary source of oxidative stress in heart failure." (PMID 37845840, 2024). "Among the genes examined were Cdk8, for which increased transgenic expression in mice promotes heart failure, TGFβ that exhibits elevated levels in myocardial infarction, and Nox4 that is a major source of reactive oxygen species." (PMID 38628440, 2024). "NOX 2 and NOX4 have been demonstrated to contribute to heart failure-induced skeletal muscle abnormalities." (PMID 37362442, 2023). "Consistent with previous reports of increased NOX4 expression in heart failure, NOX4 was also upregulated in DMD hiPSC-CMs." (PMID 37240001, 2023). "Knockdown of toll-like receptor 4 (TLR4) or NADPH oxidase 4 (NOX4) restrained ferroptosis and autophagy, which attenuated the loss of cardiomyocytes and delayed the progression of heart failure." (PMID 35677693, 2022). "It is suggested that HucMSC-EVs inhibit DOX-induced heart failure through the miR-100-5p/NOX4 pathway." (PMID 34513812, 2021). "Compared with patients with normal left ventricular function, heart failure patients had over two-fold higher superoxide generation and higher expression of the NOX4 and p67phox protein in saphenous vein segments obtained during coronary artery bypass surgery." (PMID 34440716, 2021). "Taken together, these data indicate that EV miR-100-5-p treatment inhibits DOX-induced heart failure via targeting the NOX4 protein in AC16 cells, which is similar to the effects of HucMSC-EV treatment." (PMID 34513812, 2021). "In conclusion, these results indicate that HucMSC-EVs inhibit DOX-induced heart failure through the miR-100-5p/NOX4 pathway." (PMID 34513812, 2021). "Another study reported that the upregulation of NOX4 in the heart induced cardiac remodeling, suggesting its potential role to reduce the severity of established heart failure." (PMID 33308225, 2020). "A steady overexpression of NOX-2 and NOX-4 were depicted in heart failure patients, and the deletion of NOX-4 was observed to inhibit 80% development of CH in rats." (PMID 32295034, 2020). "The full length NOX4 is significantly upregulated in ischemic cardiomyopathy suggesting a role for NOX4 in ROS production during heart failure." (PMID 29204124, 2017). "Now, Nox4 as a key molecule mediating oxidative stress and apoptosis of cardiac myocytes, it serves as an important target of heart failure treatment." (PMID 28230797, 2017). "Deep RNA sequencing of the cardiac transcriptome indicated extensive alternative splicing of the NOX4 gene in heart failure as compared to samples from healthy donor hearts." (PMID 29204124, 2017). "The full length NOX4 is significantly upregulated in heart failure, while a smaller 28-kDa isoform shows downregulation in ischemic failing hearts." (PMID 29204124, 2017). "Up-regulation of Nox4 also directly affects increased mitochondrial oxidative stress and consequent mitochondrial dysfunction and cell death during heart failure." (PMID 22808054, 2012).